EGFR (epidermal growth factor receptor)
Diseases named in the same sentence as EGFR in open-access papers (continued):
Sharing a sentence is not in itself a finding about the gene and the disease.
lung adenocarcinoma (continued). "Downregulated MUC4 has previously been shown to promote tumor progression in EGFR-mutated lung adenocarcinoma." (PMID 37111289, 2023). "These candidates were validated using ELISA and increased levels were associated with poor patient survival specifically in EGFR mutant lung adenocarcinoma patients." (PMID 38260835, 2023). "The most common histological type of NSCLC is lung adenocarcinoma, which has a higher EGFR mutation rate than other subtypes." (PMID 37014500, 2023). "The expression of CD44v9 is associated with initial stage lung adenocarcinoma and epidermal growth factor receptor mutations in lung malignancies." (PMID 38202898, 2023). "With this in mind, we developed machine learning models that predict EGFR mutational status on real-world H&E lung adenocarcinoma images with high morphological diversity and show the potential for use as screening algorithms with high NPV." (PMID 36927889, 2023). "Studies have shown that clinical parameters such as gender, smoking history, and the presence of ground-glass opacity (GGO) are closely related to the EGFR mutation status in lung adenocarcinoma." (PMID 37014500, 2023). "This article presents a case of a 62-year-old Vietnamese woman with a history of Lynch syndrome (LS), who developed lung adenocarcinoma with EGFR L858R mutation." (PMID 37901336, 2023). "TKIs are widely used in cancers with EGFR tyrosine kinase activating mutations as drivers, most effectively in lung adenocarcinoma, specifically NSCLC." (PMID 37720348, 2023). "First/second-generation TKIs are effective in treating EGFR-mutated lung adenocarcinoma patients due to the longer progression-free survival (PFS) than chemotherapy." (PMID 37697337, 2023). "Previous investigations on evaluating the EGFR mutation status in lung adenocarcinoma mainly focused on primary tumors or brain metastases." (PMID 37143947, 2023). "We did not observe an association between hormone receptor status with BRCA1, BRCA2 or EGFR mutation status in lung adenocarcinoma patients." (PMID 37461096, 2023). "Our study clearly demonstrated the clinical perspective regarding sequential treatments with first-line bevacizumab combined with 1st/2nd-generation EGFR-TKIs in advanced lung adenocarcinoma patients harboring EGFR mutations." (PMID 37854677, 2023). "Cancer and oncology genome mapping (CGA) showed that EGFR mutations were most common in female lung adenocarcinoma patients, while mutations in RNA-binding motif protein 10 (RBM10) were most common in male lung adenocarcinoma patients." (PMID 37509501, 2023). "A recent study revealed that vascular endothelial growth factor C (VEGF‐C) is closely associated with EGFR‐TKI resistance in lung adenocarcinoma." (PMID 37605832, 2023). "It has also been shown that several CT features, such as maximum tumor diameter, tumor location, density, ground-glass opacity, pleural traction, and air bronchogram, denote EGFR mutation status in lung adenocarcinoma." (PMID 38094613, 2023). "The data suggests that osimertinib is effective in treating bone metastases in patients with EGFR 19Del mutated lung adenocarcinoma." (PMID 37653755, 2023). "These cases suggest that osimertinib is a promising treatment option for patients with EGFR 19 deletion-mutated lung adenocarcinoma and bone metastases, although further clinical studies are needed to confirm its efficacy." (PMID 37653755, 2023). "The clinicopathological presentation of early-stage lung adenocarcinoma patients with epidermal growth factor receptor (EGFR) mutations has been seldom studied." (PMID 36766495, 2023). "Among the originally reported tumors with EGFR mutations, three were classified as fine bronchioloalveolar carcinomas, suggesting a higher prevalence of EGFR mutations in adenocarcinomas of the lung with features of fine bronchioloalveolar carcinoma." (PMID 38077251, 2023).
lung adenocarcinoma (continued). "EGFR driver mutations are the most common, particularly in Asians, women, and nonsmokers, and more than 40% of Japanese patients with lung adenocarcinoma are EGFR mutation-positive (EGFRm+)." (PMID 38248726, 2023). "An epidermal growth factor receptor (EGFR) mutation is a robust prognostic factor for patients with recurrent or advanced lung adenocarcinoma (ADC)." (PMID 37930012, 2023). "In this work, we propose a radiogenomic workflow to detect the presence of KRAS and EGFR mutations using radiomic features extracted from computed tomography images of patients affected by lung adenocarcinoma." (PMID 37508774, 2023). "Compared with systemic chemotherapy, EGFR-TKI targeted combined chemotherapy for stage-IV lung adenocarcinoma is associated with enhanced immune function of patients." (PMID 37250563, 2023). "Overall, we first reported the cases of 2 lung adenocarcinoma patients harboring EGFR ex20ins mutations (p.S768_D770dupSVD and p.N771_P772insVal) who received furmonertinib as first-line treatment and achieved PFS times of 8.13 and 10.90 months, respectively." (PMID 38206746, 2023). "Patients with advanced lung adenocarcinoma with EGFR mutations benefit considerably from treatment with EGFR-TKIs." (PMID 37390230, 2023). "This study aimed to assess the relationship between EGFR mutations and smoking patterns in patients diagnosed with lung adenocarcinoma referred to major pathologic laboratories." (PMID 37425232, 2023). "Osimertinib is a third-generation epidermal growth factor receptor and tyrosine kinase inhibitor (EGFR-TKI) approved for the treatment of lung adenocarcinoma patients harboring EGFR mutations." (PMID 37190191, 2023). "In this report, we present a case of stage IV lung adenocarcinoma with both epidermal growth factor receptor and anaplastic lymphoma kinase mutations, along with high PD-L1 expression." (PMID 37705536, 2023). "Osimertinib shows promise as a clinical option for patients with EGFR 19del mutated lung adenocarcinoma and bone metastases, but further clinical studies are necessary to demonstrate its efficacy." (PMID 37653755, 2023). "Between January 2015 and December 2020, data for 102 advanced EGFR-mutated lung adenocarcinoma patients receiving first-line bevacizumab combined with erlotinib or afatinib followed by treatments at multiple institutions were retrospectively analyzed." (PMID 37854677, 2023). "The prognostic impact of EGFR mutation as major targetable somatic gene variant on lung adenocarcinoma is controversial." (PMID 36918771, 2023). "This study aims to evaluate features from T1W and T2FS MRI and important clinical factors from lung adenocarcinoma patients with spinal metastases, and to develop a radiomics nomogram for prediction of the EGFR mutation and subtypes." (PMID 37143947, 2023). "The implication of this finding is that patients with lung adenocarcinoma harboring EGFR mutations can be treated with EGFR tyrosine kinase inhibitors (TKIs), improving survival in such patients." (PMID 37371673, 2023). "Osimertinib is a third-generation drug that belongs to the epidermal growth factor receptor (EGFR) tyrosine kinase inhibitors (TKIs) used in advanced lung adenocarcinoma with EGFR mutations." (PMID 38069210, 2023). "Our study showed extremely high agreement rates in detecting the most common EGFR alterations in lung adenocarcinomas (for detection of the T790M mutation, a 100% concordance rate between IdyllaTM and Therascreen® was observed)." (PMID 37047382, 2023). "Early clinical studies have revealed that human lung adenocarcinoma (LA) harboring oncogenic EGFR mutations is resistant to ICIs5–7." (PMID 36991099, 2023). "About 20% of patients with lung adenocarcinoma have EGFR mutations, such as exon 19 deletions and exon 21 (L858R) point mutations." (PMID 36900362, 2023).
lung adenocarcinoma (continued). "We conducted a multicenter, retrospective cohort study to investigate the impacts of adding LCT on targeting the primary tumor mass in patients with susceptible EGFR-mutant lung adenocarcinoma treated with first-line afatinib." (PMID 37046679, 2023). "It is shown that miR-630 expression levels are related to gefitinib resistance via miR-630/YAP1/ERK feedback loop in EGFR-mutated lung adenocarcinoma cells." (PMID 37697308, 2023). "In this study of EGFR mutation‐positive early lung adenocarcinoma, the presence of several signaling pathway clusters showing characteristic differences among AISs, MIAs, and SIAs was suggested." (PMID 37004157, 2023). "In the Asian population, 50–60% of lung adenocarcinoma patients have EGFR-sensitive mutations (the exon 19 deletion mutation and the exon 21 L858R point mutation)." (PMID 37239162, 2023). "Epidermal growth factor receptor (EGFR) mutation is an important driver gene mutation for lung adenocarcinoma." (PMID 37035883, 2023). "We enrolled 767 patients from 4 cohorts who were pathologically diagnosed with lung adenocarcinoma and EGFR mutation status." (PMID 37223682, 2023). "Firstly, we employed A549 cells as a model for EGFR-TKI-resistant lung adenocarcinoma, which harbors wild-type EGFR and KRAS mutation." (PMID 37886957, 2023). "The study enrolled 115 lung adenocarcinoma patients with EGFR mutation status from June 2016 and September 2017." (PMID 36810090, 2023). "Here, we present 2 patients with advanced lung adenocarcinoma harboring EGFR ex20ins mutation who responded well to first-line furmonertinib, achieving progression-free survival (PFS) of 8.13 months and 10.90 months, respectively." (PMID 38206746, 2023). "In individuals with lung adenocarcinoma, up to 20% exhibit mutations in the ERBB1 gene, which encodes the EGFR protein." (PMID 37895255, 2023). "Oncogenic mutations in the EGFR gene are targets of tyrosine kinase inhibitors (TKIs) in lung adenocarcinoma (LC) patients, and their search is mandatory to make decisions on treatment strategies." (PMID 37047382, 2023). "The efficacy and safety of EGFR-TKIs alone versus EGFR-TKIs plus chemotherapy for treatment of advanced lung adenocarcinoma with EGFR 19Del, L858R mutation still needs to be further investigated in large prospective clinical trials." (PMID 37390279, 2023). "We developed a multiple-instance model to predict EGFR mutational status in lung adenocarcinoma samples with diverse tissue morphologies, achieving an AUC of 0.870 with an NPV of 0.954 and a PPV of 0.410." (PMID 36927889, 2023). "The aim of this study was to enhance the comprehension of radiomic features linked with KRAS and EGFR mutations in lung adenocarcinoma and evaluate the effectiveness of these features in accurately classifying mutations." (PMID 37508774, 2023). "Lung adenocarcinomas with common EGFR mutations are often responsive to EGFR TKIs, while uncommon and compound mutations react unpredictably." (PMID 36923435, 2023). "The secondary T790M EGFR mutation appears in advanced lung adenocarcinoma with acquired resistance due to prior bevacizumab treatment combined with erlotinib or afatinib, and osimertinib is administered as a subsequent therapy for T790M-positive patients." (PMID 37854677, 2023). "The general approach described here is applicable for investigating Ras functions in other cancer cell line models characterized by driver kinase mutations such as EGFR-mutant lung adenocarcinoma and BRAF-mutant melanoma cell lines." (PMID 37681415, 2023).
lung adenocarcinoma (continued). "The [18F]FDG PET/CT radiomics models constructed using machine learning algorithms were a potential non-invasive method to identify EGFR mutation status in patients with lung adenocarcinoma." (PMID 37014500, 2023). "Both the EVIDENCE and CONVINCE studies demonstrated that icotinib considerably reduced DFS and serious adverse effects compared to chemotherapy for patients with EGFR-mutated lung adenocarcinoma." (PMID 37251922, 2023). "Our study found that the predictive ability of SUVmax for EGFR mutation status was weak (AUC: 0.584), possibly because our study only included lung adenocarcinomas." (PMID 37014500, 2023). "A study on early lung adenocarcinoma with EGFR mutation found that the infiltrating T cell types were mainly exhausted and regulatory T cells, which were associated with an increase in dendritic cells expressing the CD1c gene precisely." (PMID 38099311, 2023). "In this study, we retrospectively enrolled patients with advanced lung adenocarcinomas harboring susceptible EGFR mutations who were diagnosed and treated with first-line afatinib in three hospitals." (PMID 37046679, 2023). "Epidermal growth factor receptor-tyrosine kinase inhibitors (EGFR-TKIs) have become the first-line treatment for patients with advanced lung adenocarcinoma with EGFR-sensitive mutations." (PMID 37287014, 2023). "This study tried different feature engineering-based radiomic paths to predict the status of EGFR mutation for patients with lung adenocarcinoma." (PMID 36810090, 2023). "Identifying EGFR mutation status in lung adenocarcinoma using 18F-FDG PET/CT radiomics is promising, but limitations remain." (PMID 38094613, 2023). "Detected in more than 50% of late-stage lung adenocarcinoma in Asian patients, the EGFR mutation was regarded as a golden mutation for Asians." (PMID 37189759, 2023). "In the following, to further analyze the differences in MMP11 expression at the mRNA level in lung adenocarcinoma tissues under different EGFR mutation conditions, we obtained 512 samples with known EGFR mutation conditions from the TCGA-LUAD dataset." (PMID 36756152, 2023). "This can be attributed to the fact that EGFR mutation is the most common driver mutation gene in Asia, which accounts for approximately 50–60% of patients with lung adenocarcinoma compared to 10–20% in Caucasian patients." (PMID 37873790, 2023). "This proteomic assay was used to identify proteins related to HSP90 inhibition responsiveness according to the most relevant molecular alteration in lung adenocarcinoma such as EGFR and KRAS mutations and ALK translocation." (PMID 37762133, 2023). "The most common type of mutation in EGFR is exon 19 E746_S752delinsV, an extremely rare mutation in EGFR mutant lung adenocarcinoma; KRAS and HRAS mutations are at codons 12 and 13; all AKT 1 mutations are restricted to the E17K mutation." (PMID 38115282, 2023). "In various human cancers, e.g., lung adenocarcinomas; EGFR gene mutation is present in 10%–20% of the patients with African and European ancestry and thereby serves as an excellent biomarker and therapeutic target." (PMID 37810173, 2023). "EGFR-sensitizing mutations are the most common targetable driver mutations observed in lung adenocarcinoma." (PMID 38328605, 2023). "We found that combined models showed great promise in predicting the EGFR mutation status of lung adenocarcinoma patients." (PMID 37749461, 2023). "The genes whose loss is predicted to be detrimental to EGFR-driven tumors (i.e., Keap1, Lkb1, and Nf2) are rarely co-mutated with EGFR in human lung adenocarcinoma as predicted." (PMID 37828026, 2023). "Downregulation of Cav1 has been reported to enhance sensitivity towards EGFR-TKIs in lung adenocarcinoma cells (PC9) harboring EGFR mutations." (PMID 37696458, 2023). "Kirsten rat sarcoma viral oncogene homolog (KRAS) and epidermal growth factor receptor (EGFR) are the most frequently mutated oncogenes in human lung adenocarcinoma." (PMID 37985999, 2023).
lung adenocarcinoma (continued). "We investigated the relationship between 18F-fluorodeoxyglucose (FDG) positron emission tomography (PET) texture indices and EGFR mutation status in patients with newly diagnosed lung adenocarcinoma." (PMID 37185611, 2023). "Afatinib is a promising EGFR-TKI therapy for those with advanced lung adenocarcinomas harboring susceptible EGFR mutations." (PMID 37046679, 2023). "In terms of treatment trajectories, patient 1 was a 75-year-old female ex-smoker with clinical stage IIIa (cT4N0M0; T4 due to tumor size) EGFR-mutated invasive acinar-predominant lung adenocarcinoma." (PMID 39790537, 2023). "EGFR mutation-positive patients with pleural metastasis of lung adenocarcinoma diagnosed in the Department of Respiratory Medicine of Yuhuangding Hospital of Yantai City, Shandong Province, from January 2014 to January 2022 were selected." (PMID 37390230, 2023). "Identifying EGFR mutation status and main subtypes of patients with lung adenocarcinoma are beneficial in making EGFR-TKIs-related treatment strategies in clinic." (PMID 37223682, 2023). "Tyrosine kinase inhibitors (TKIs) that specifically target mutational points in the EGFR gene have significantly reduced suffering and provided greater relief to patients with lung adenocarcinoma (LUAD)." (PMID 37393311, 2023). "Lung adenocarcinoma with activated epidermal growth factor receptor (EGFR) mutations is dependent on EGFR signaling for survival and proliferation." (PMID 36961882, 2023). "Studies on applying 18F-FDG PET/CT TSR in predicting EGFR mutations in patients with lung adenocarcinoma." (PMID 38094613, 2023). "Epidermal growth factor receptor (EGFR) mutations occur in about 50% of lung adenocarcinomas in Asia and about 15% in the US." (PMID 36875137, 2023). "C1orf74, also known as URCL4, has been reported to have higher expression and be associated with poor prognosis in lung adenocarcinoma patients, and its role in regulation of the EGFR/AKT/mTORC1 pathway has been recently elucidated." (PMID 37947608, 2023). "The results showed that smoking history and CEA grouping significantly affected the relationship between SUVmax and EGFR mutation in lung adenocarcinoma (both p < 0.05), suggesting that there was an interaction effect." (PMID 36983578, 2023). "This study therefore aimed to investigate the clinical efficacy and prognosis traits of EGFR-TKIs alone versus EGFR-TKIs plus chemotherapy for advanced lung adenocarcinoma with EGFR 19Del, L858R mutation." (PMID 37390279, 2023). "For patients with early-stage lung adenocarcinoma, curative surgery is the standard treatment; some studies have pointed out that patients with early-stage lung adenocarcinoma with EGFR mutations have a lower recurrence rate after surgery." (PMID 36766495, 2023). "The development of an optimized 18F-FDG PET/CT radiomics model, predicting EGFR mutation status and prognosis in lung adenocarcinoma, was realized through a multicenter study." (PMID 38027000, 2023). "High pretreatment levels of neutrophil to lymphocyte ratio and platelet to lymphocyte ratio were strongly associated with a worse prognosis in stage I EGFR-altered lung adenocarcinomas." (PMID 37941434, 2023). "Epidermal growth factor receptor (EGFR) mutation is a predictor of responsiveness to lung-adenocarcinoma-targeted drug tyrosine-kinase inhibitor (TKI) therapy." (PMID 36766495, 2023). "Inhibition of the HSP90 chaperone was evaluated in different lung adenocarcinoma cell lines representing the most relevant molecular alterations (EGFR mutations, KRAS mutations, or EML4-ALK translocation) and wild-type genes found in each tumor subtype." (PMID 37762133, 2023). "EGFR mutations in EXOs of malignant pleural effusion of lung adenocarcinoma patients reported 100% agreement for EGFR genotyping with the primary tumour." (PMID 37296932, 2023). "An analysis was conducted to investigate differences in EGFR mutations among various ethnic populations with lung adenocarcinomas." (PMID 37895255, 2023).